ATM (ATM serine/threonine kinase)
Diseases named in the same sentence as ATM in open-access papers (continued):
Sharing a sentence is not in itself a finding about the gene and the disease.
tumor (continued). "Variants in the CHEK2, BRCA2 and ATM tumor suppressor genes, as well as the ASXL1 and EZH2 Epigenetic Regulators, may support the self-renewal of the proliferating progenitors." (PMID 35896598, 2022). "In addition to initiating tumorigenesis by mediating the deletion of Pten, Cre recombinase acted in tumor-initiating cells to delete one or both floxed alleles of ATM." (PMID 36139666, 2022). "Mutations in ATM including the FAT domain were found in PCa indicating that the dysfunction of this kinase may affect the fate of this tumor." (PMID 35347810, 2022). "The synergy of a combined EZH2/ATM inhibition in BRCA1-deficient tumor cells could be demonstrated by using several small molecule inhibitors of EZH2 (GSK126, ZLD1039) and ATM (AZD1390, KU60019) that are currently at various stages of preclinical development." (PMID 35715861, 2022). "Importantly, tumor-specific alterations such as ATM loss and Cyclin E1 (CCNE1) amplification are more sensitive to ATR inhibition and are being exploited in synthetic lethality (SL) strategy." (PMID 35458687, 2022). "ATM germ-line heterozygosity has been described to increase tumor susceptibility." (PMID 33494414, 2021). "On the other hand, R-2-HG could elicit the downregulation of DNA damage sensor ataxia telangiectasia mutated (ATM) and subsequently increase the impairment of DNA repair, finally enhance the sensitivity of tumor cells to alkylating agents." (PMID 34425876, 2021). "In fact, ATM mutations increase the risk for development of a second tumor after RT." (PMID 34068084, 2021). "In addition, FBXW7 and ATM mutations were significantly associated with higher tumor stage (p = 0.03191 and 0.01237, respectively)." (PMID 33854094, 2021). "It is well known that ATM germline mutations have different effects on tumor cells." (PMID 34068084, 2021). "High ATM expression in pancreatic NENs was associated with higher tumour differentiation, lower tumour size, lower recurrence rate and better prognosis, while loss of ATM expression was common in metastasized disease and resulted to be associated with a worse prognosis." (PMID 32935263, 2021). "The CSig3(+) ATM-BAL tumor also had a CHEK2 truncating kinase domain mutation." (PMID 34877933, 2021). "Interestingly, STING-activity is also upregulated in the setting of DDR deficiencies including BRCA1/2 and ATM mutant tumor cells." (PMID 34631532, 2021). "Similarly, CRISPR-Cas9 mediated knockout of ataxia-telangiectasia mutated (ATM) gene, a tumor suppressor, in two human GBM cell lines such as LN18 and LN229 potentiated autophagy and increased their responsiveness to platinum treatment." (PMID 34571991, 2021). "Although the impact of sub-clonality and ATM deficiency in solid tumours is less well established, once ATM deficiency is robustly clinically defined it will be important to study primary samples across various tumour types to assess the impact of clonal divergence on ATM deficiency and response." (PMID 32444694, 2020).
tumor (continued). "Combined treatment with olaparib plus ATR inhibition with VE821 induced cell death only in ATM-deficient A549 cells, suggesting that patients with ATM-deficient tumours could benefit from a combination of PARP and ATR inhibitors." (PMID 32183301, 2020). "Finally, we assessed the impact of combined olaparib/AZD6738 treatment on ATM-deficient tumours in vivo." (PMID 32444694, 2020). "In addition, NB tumours with MYCN amplification or ATM deficiency have been shown to have increased sensitivity to single agent olaparib treatment." (PMID 32354033, 2020). "Work from our lab and others discussed here has shown that PARP inhibitors may also have potential in treating patients with ATM-deficient tumours." (PMID 32183301, 2020). "ATM alterations may have harmful effects facilitating tumor progression due to functional loss beyond its role in DNA repair." (PMID 33098265, 2020). "Alongside a previous report, these pre-clinical findings suggest that combined olaparib/AZD6738 treatments may provide more durable responses than single-agents in ATM-deficient tumours across multiple tissues types with varying degrees of ATM-deficiency." (PMID 32444694, 2020). "In addition, patients who had ≥3 DDR alterations (including ATM) showed substantially higher tumor mutation burden [TMB] [mean 32.5 mutations/Mb (range 14–72) versus mean 12.4 mutations/Mb (range 0.9–78), p = 0.01]." (PMID 33098265, 2020). "Patients with tumours characterised by ATM-deficiency may benefit from treatment with a PARP inhibitor in combination with an ATR inhibitor." (PMID 31481733, 2019). "Single agent activity of PARP inhibitors has been demonstrated in ATM-deficient tumor cells." (PMID 30975222, 2019). "Tumours with high MYC and low ATM expressions were significantly associated with higher tumour grade, tumour type, pleomorphism, high mitotic index, ER−, PR−, triple negative, basal phenotypes and high-risk Nottingham Prognostic Index (NPI) (all adjusted p values ≤ 0.001)." (PMID 30746633, 2019). "The results revealed a weak-to-absent staining in the proband’s tumor as compared to normal surrounding tissue, also suggesting that the germline ATM c.3806A > G may be implicated in tumor development." (PMID 31811167, 2019). "Somatic ATM truncating mutation was identified in 1 tumor (K1057*)." (PMID 31124283, 2019). "Therefore, they concluded that the ATM and cyclin D1 under and over expressions respectively can be associated with tumor progression among the Iranian BC patients." (PMID 31286981, 2019). "Finally, no consistent pattern of loss of the normal allele was reported in an Australian series (N = 17) or in a French series (N = 16) of tumours from carriers of putative BC-associated ATM variants." (PMID 29665859, 2018). "Tumor tissues harboring ATM/RB1 mutations may have increased mutation rates due to DNA repair defect." (PMID 29682192, 2018). "In addition, we detected a frameshift mutation in ATM that has become homozygous through an LoH event and is fixed in the tumor sample (allele frequency = 0.955)." (PMID 30301885, 2018). "In addition, we determined the functional role of ATM-associated DNA damage in the development of T-cell senescence induced by tumor-derived γδ Treg cells." (PMID 29339767, 2018). "In addition, 70% of ATM-associated tumours showed copy number losses at 13q14.11-q14.3, 17p13.2-p12 and 21p11.2-p11.1." (PMID 29665859, 2018). "In addition, we performed whole-genome sequencing on four tumours from ATM loss-of-function variant carriers with available frozen material." (PMID 29665859, 2018). "Notably, the expression of these four miR‐BARTs represented more than 10% of all EBV‐encoded miRNAs in tumor cells, while downregulation of ATM expression was commonly detected in all of our tested sequenced samples." (PMID 29230817, 2018).
tumor (continued). "Nonetheless, hallmarks of ATM-associated tumours were found and could help to identify ATM variant carriers outside an A-T context or an HBOC family context." (PMID 29665859, 2018). "This raises a question of whether novel agents targeting DDR and HR deficiency would also work in ATM-mutated tumours." (PMID 29329208, 2018). "However, there were two rare germline ATM missense mutations that rose to fixation in all three of the tumor samples from that patient through complete LoH." (PMID 30301885, 2018). "With regard to ATM-associated tumours, one cannot exclude the possibility that biallelic inactivation of ATM occurs through promoter methylation of the gene in the seven tumours not showing LOH at the ATM locus or through point or small-size sequence variation." (PMID 29665859, 2018). "Unfortunately, in our study protein expression analysis could not be performed to validate the diminution of expression of these genes in ATM-associated tumours, owing to limited material." (PMID 29665859, 2018). "Thus, we investigated if partial or total ATM-deficiency affects the response of pancreatic cells to DNA damage-inducing agents by exposing our KC and KCATMΔΔ primary tumor cells to X-ray or γ-irradiation (IR)." (PMID 28894253, 2017). "Less is known about the effects of ATM mutations found in various tumor types and the mechanisms by which they might promote oncogenesis." (PMID 28476018, 2017). "Together, our data shows that tumour ATM loss has prognostic significance in early stage NSCLC, and could identify a unique cohort of patients who can benefit from disease-modifying therapy." (PMID 28418844, 2017). "Interestingly, loss of ATM activity is a hallmark of various tumor types and RSV can bind to ATM increasing autophosphorylation and substrate phosphorylation." (PMID 29267250, 2017). "The ATM-EI should be a more stringent measure of ATM loss in tumours, and we hypothesized that increased genomic instability associated with ATM loss in the early stages of NSCLC and would be associated with a worse clinical outcome." (PMID 28418844, 2017). "Furthermore, in an analysis of listed mutations in 500 human protein kinases in 169 primary tumours and 40 cell lines, mutations in ATM emerged at number 3 in terms of frequency." (PMID 28418844, 2017). "The presence of an ATM mutation leads to a dysfunction in the repair process for DNA double-strand breaks and consequently could render the tumor more chemo-sensitive, especially to platinum agents, according to the literature." (PMID 28086948, 2017). "The first and strongest hypothesis is that the observed response is explained by the presence of an ATM mutation in this tumor." (PMID 28086948, 2017). "It is possible that in some tumours that are shown to be ATM deficient by IHC, ATM functionality is still preserved, while in other cases ample ATM expression by IHC could be detecting non-functional, truncated protein." (PMID 28418844, 2017). "This analysis is arguably more biologically relevant, as the genomic instability induced by ATM loss specifically in the cancerous cells could drive progression of the tumor." (PMID 28418844, 2017). "Similarly, ATM (ataxia telangiectasia mutated) gene, which encodes for a serine-threonine kinase and belongs to the phosphatidylinositol-3 kinase (PI-3K) family, acts as an important tumor suppressor gene." (PMID 27119356, 2016). "Our results indicated that germline truncation and missense variants in several genes were under selection in the tumour, with ATM, BRCA1, BRCA2 and RAD51C determined as significant from both truncation and missense analyses and BAP1, BRIP1, FANCM, PALB2 and RAD51D from truncation analysis alone." (PMID 26689913, 2015).
tumor (continued). "We sequenced all DNA samples from normal and tumor tissues that had potential ATM mutations." (PMID 25625042, 2015). "In addition, we found the biallelic inactivation of ATM by both a germline and a somatic deleterious mutation in the tumor of one patient." (PMID 26506520, 2015). "Importantly, AZD6738 strongly synergizes with cisplatin in ATM-deficient models of NSCLC, and causes near complete tumor regression in an ATM-deficient xenograft model." (PMID 26517239, 2015). "This indicates that loss of ATM is associated with a less differentiated tumour phenotype." (PMID 26220524, 2015). "Deregulation of cell cycle check point may lead to tumorigenic events during which the ataxia telangiectasia mutated (ATM)/ATM Rad3- related (ATR) regulated checkpoint act as a guard against tumour progression." (PMID 24972086, 2014). "Another postulated mechanism is that both tumours share the same aetiological factors, with mutation in the ataxia telangiectasia mutated (ATM) tumour suppressor gene, as well as infection with the Epstein-Barr virus (EBV) and mouse mammary tumour virus (MMTV) all currently implicated." (PMID 24708809, 2014). "It deleted 62 RefSeq genes including ATM (ataxia telangiectasia mutated), a gene that encodes for a cell cycle checkpoint phosphorylating kinase that functions for regulating proteins for tumor suppression, checkpoint, DNA repair and maintenance of genome stability." (PMID 23369149, 2013). "Anti-tumor activity mediated by panobinostat/BEZ235 combination was associated with sustained or increased levels of DNA damage with concurrent reduction of the DDR protein ATM." (PMID 24163230, 2013). "Whether the FA pathway inhibitors specifically kill ATM-deficient tumor cells is another important question." (PMID 22537224, 2012). "The FA deficient tumor cells are, thus, hypersensitive to ATM inhibition." (PMID 19371427, 2009). "Furthermore, ATM deficiency might influence the tumor microenvironment, impacting the movement and activity of immune cells, possibly by changing the production rate of cytokines or chemokines that attract or suppress immune cells." (PMID 40310425, 2025). "Blocking ATM-related DNA damage in T cells could prevent T cell aging mediated by tumor-associated factors and Treg cells in vitro, and enhance antitumor immunity and the effectiveness of immunotherapy in vivo in the context of adoptive transfer T cell therapy." (PMID 40075162, 2025). "Future work will leverage these data to interrogate tumor immune and vascular microenvironment alterations induced by irradiation and Atm loss, which may guide the rational design of combinations of RT, ATM inhibitors, and therapies targeting the immune system or vasculature." (PMID 40244686, 2025). "However, tumor growth inhibition was enhanced considerably in ATM-deficient Mino xenografts." (PMID 40608419, 2025). "In preclinical models, axitinib has been reported to trigger cellular senescence both in tumor as well as in normal cells, through a mechanism involving intracellular reactive oxygen species (ROS) accumulation and activation of Ataxia Telangiectasia Mutated kinase (ATM)." (PMID 39377544, 2024). "While the PALB2 expression-cutoff for haplosufficiency is unknown, we previously showed that variants expressing ≥ 30% of the ATM full-length transcript cannot be classified as pathogenic or, in other words, these variants would keep their tumor-suppressor activity." (PMID 39518003, 2024). "Therefore, ATM mutant/protein-loss tumours likely represent a heterogenous population." (PMID 37627223, 2023).
tumor (continued). "Notably, for patient BR360006, none of the plasma variants was detected in NGS of the matched tumor; however, by employing our tumor-agnostic approach, an ATM Q3000H mutation and a KIT C537W mutation were classified as tumor derived and evaluated for ctDNA kinetics." (PMID 37814061, 2023). "Therefore, it is possible that the concurrent FA/HR aberrations and ATM/ATR mutations help fine-tune the DDR machinery to introduce enough mutations to drive tumorigenesis/tumor progression while keeping certain levels of genomic integrity to maintain tumor cell survival." (PMID 38041093, 2023). "Since the antioxidant treatment of ATM-null mice improves intrinsic defects in stem cell renewal and might contribute to the delay of their tumor onset, it has been hypothesized that augmented accumulation of intracellular ROS, associated with ATM impairments, may contribute to these diseases." (PMID 36290706, 2022). "Interestingly, the variants in ATM were only present in the TMB-H tumours." (PMID 35740599, 2022). "Our data reveal CHK1 as a potential partner for co-inhibition with IGF blockade; we suggest that the efficacy of this combination may be most appropriately tested in ATM null tumours given our recent identification of ATM loss as a candidate biomarker for sensitivity to IGF axis blockade." (PMID 34773074, 2022). "Notably, we identified a mutation shared by T2 and R1 in ATM, a gene that is implicated in chemotherapy resistance and which may have conferred this phenotype to the recurrent tumour." (PMID 34299215, 2021). "Furthermore, tumor suppressor effect of “tuberous sclerosis complex 2” protein (TSC2) activated by ROS induced “ataxia-telangiectasia mutated” (ATM) protein may have also decreased the expression of mTORC1 gene." (PMID 33539381, 2021). "Indeed, the loss of ATM activity has been observed in various tumor types." (PMID 29267250, 2017). "Thus, ATM loss may allow tumor cells a proliferation and survival advantage, while mutations that inactivate ATM kinase and ATR loss may be lethal." (PMID 27259260, 2016). "We speculated that many phosphatases can inactivate ATM when DNA damage repair progresses, but functional mutations of phosphatases ubiquitously found in the tumor cells (e.g. PP2A mutation) might reduce the inactivation efficiency of ATM (as the third term in Eq.1 in mutant ATM switch)." (PMID 19545411, 2009). "Circulating tumor DNA (ctDNA) is the most clinically advanced analyte, supporting detection of actionable alterations such as BRCA1/2 and ATM mutations, guiding targeted therapies, and enabling real-time monitoring of treatment response and resistance." (PMID 42122162, 2026). "Loss of ATM function enhances tumour dependence on ATR signalling; therefore, ATM mutation or deletion is considered a potential predictive biomarker for ATRis." (PMID 41537447, 2026). "PARP inhibitors target DNA damage repair pathways leading to synthetic lethality of tumor cells with HRR deficiency, e.g., due to variants in genes such as ATM or BRCA2." (PMID 41546701, 2026).